ERBB3 (erb-b2 receptor tyrosine kinase 3)
Diseases named in the same sentence as ERBB3 in open-access papers (continued):
Sharing a sentence is not in itself a finding about the gene and the disease.
renal cell carcinoma (4 papers, 2020 to 2025). "In parallel, the study employed GSEA to assess the gene set enrichment resulting from ERBB3 isoform overexpression, specifically in the context of renal cell carcinoma." (PMID 38276060, 2024). "Researching the functions and expressions of ERBB3 isoforms is important for creating targeted therapies and improving patient outcomes in renal cell carcinoma (RCC), a type of cancer that has a very complex genetic landscape." (PMID 38276060, 2024). "ERBB3, a member of the ERBB family of receptor tyrosine kinases, has emerged as a key player in the pathogenesis of various cancers, including renal cell carcinoma (RCC)." (PMID 38276060, 2024). "Plus, the expression of ErbB3 has not been thoroughly studied in renal cell carcinoma." (PMID 31701684, 2020).
urothelial carcinoma (4 papers, 2015 to 2023). A malignant neoplasm derived from the transitional epithelium of the urinary tract (urinary bladder, ureter, urethra, or renal pelvis). "A functional genetic screen has found that feedback activation of ErbB3 (Erb-B2 receptor tyrosine kinase 3) signaling pathway can reduce the sensitivity of AZD4547 through activation of downstream PI3K pathway in urothelial carcinoma." (PMID 33568192, 2021). "To clarify the molecular context in which ERBB2 and EGFR gene amplifications and overexpression occur we performed an in-depth study of EGFR, ERBB2, and ERBB3 alterations in relation to existing urothelial carcinoma molecular subtypes." (PMID 28388586, 2017). "Here we investigate EGFR, ERBB2 (HER2), and ERBB3 (HER3) genomic alterations and expression in relation urothelial carcinoma molecular subtypes." (PMID 28388586, 2017). "Development of ADCs which conjugate ErbB3 antibodies with payload chemotherapeutic agents may have utility in urothelial carcinoma, especially in patients who are refractory to platinum-based therapy." (PMID 37316561, 2023). "We analyzed a cohort of 599 cases of urothelial carcinoma for EGFR, ERBB2, and ERBB3 gene expression and genomic alterations." (PMID 28388586, 2017). "In essence, urothelial carcinomas could be divided into two distinct categories based on EGFR, ERBB2, and ERBB3 expression and genomic alterations." (PMID 28388586, 2017).
acute myeloid leukemia (3 papers, 2016 to 2023). Acute myeloid leukemia (AML) is a group of neoplasms arising from precursor cells committed to the myeloid cell-line differentiation. "We previously identified a rare ERBB3 germline variant that co-segregated with disease in a pedigree with familial erythroid myelodysplastic syndrome/acute myeloid leukemia (MDS/AML), implicating this gene family in predisposition to blood cancers." (PMID 34209587, 2021).
breast adenocarcinoma (3 papers, 2018 to 2021). "The antiproliferative action of the antibodies was analyzed in vitro, using two classical models of ErbB3-overexpressing breast adenocarcinomas: MCF-7 cells and SK-BR-3 cells, which also overexpress ErbB2." (PMID 34572289, 2021). "Both antibodies inhibited the ErbB3-driven proliferation of MCF-7 breast adenocarcinoma cells and HER2-overexpressing SK-BR-3 cells, with the EC50 in the range of 0.1–25 μg/mL." (PMID 34572289, 2021). "To verify that this observed enrichment was not specific to LPS-stimulated dendritic cells, or to mouse, we tested for short CpG island enrichment in a time course of human breast adenocarcinoma cells stimulated with an ErbB3/4 ligand, heregulin." (PMID 29945659, 2018).
cervical squamous cell carcinoma (3 papers, 2018 to 2022). A squamous cell carcinoma arising from the cervical epithelium. "ERBB3, a member of the ERBB family of receptor tyrosine kinases, plays an important role in cancer, despite its lack of intrinsic carcinogenic mechanism of cervical squamous cell carcinoma and endocervical adenocarcinoma (CESC)." (PMID 35581263, 2022).
Cirrhosis (3 papers, 2016 to 2024). A chronic disorder of the liver in which liver tissue becomes scarred and is partially replaced by regenerative nodules and fibrotic tissue resulting in loss of liver function. "While ERBB3 serum values were similar between patients with cirrhosis and those with HCC (p = 0.993), in the latter, serum ERBB3 ≥ 2860 RU resulted significantly and independently associated with OS (Hazard Ratio = 2.24, 95% CI 1.16–4.35, p = 0.017)." (PMID 33799723, 2021). "Additionally, research has identified ERBB3 as a potential serum marker for early HCC in patients with chronic hepatitis and cirrhosis." (PMID 38846640, 2024). "Although serum ERBB3 was not able to discriminate between patients with cirrhosis and those with HCC, we observed a potential prognostic value for the prediction of OS." (PMID 33799723, 2021). "Based on the results of the present study, the measurement of serum ERBB3 appeared unsuitable for the surveillance of patients with cirrhosis for the risk of HCC development; indeed, the biomarker was not able to discriminate between patients with cirrhosis and those with early tumor." (PMID 33799723, 2021). "Consistently, AFP showed an AUC value of 0.710, 95% CI 0.634–0.778 (p < 0.001) for the discrimination between cirrhosis and HCC, while serum ERBB3 was not able to discriminate between the two groups of patients (AUC = 0.500, 95% CI 0.421–0.579, p = 0.994)." (PMID 33799723, 2021).
diabetic nephropathy (3 papers, 2020 to 2022). "Circ_DLGAP4 induced diabetic nephropathy progression by activating ERBB3." (PMID 33230102, 2020).
liver cancer (3 papers, 2020 to 2024). An epithelial or non-epithelial malignant neoplasm that arises from the liver. "A curated panel of 30 LRIs specific to liver cancer was formulated, several of which have known associations with LC, including noteworthy ligands like SERPINC1, GPC3, and receptors such as ERBB3." (PMID 39850635, 2024). "Direct EIF3D binding was reported on the ERBB3 transcripts in human HepG2 liver cancer cells (Supplementary Excel S6)." (PMID 33273988, 2020).
lung squamous cell carcinoma (3 papers, 2021 to 2025). "As ERBB3 inhibition with a blocking antibody under development (GSK2849330) has been effective in NRG fusion-positive squamous cell carcinoma of the lung, it might be beneficial in CRPCs driven by CAF-mediated activation of ERBB3." (PMID 34283056, 2021).
medulloblastoma (3 papers, 2015 to 2021). A malignant, invasive embryonal neoplasm arising from the cerebellum. "In Pomeroy’s dataset, the expression of ERBB3 was 8.973 times higher in classic medulloblastoma tissues than in normal tissues." (PMID 33892666, 2021). "Furthermore, we show that EGFR and ErbB2 are highly and ErbB3 and ErbB4 are hardly expressed on the cell surface of our medulloblastoma cell lines." (PMID 26496080, 2015). "Flow cytometry analysis revealed that MET (mean±sd: 74.9% ± 13.9%), EGFR (mean±sd: 77.4% ± 10.9%) and ErbB2 (mean±sd: 67.8% ± 10.3%) are highly expressed in all medulloblastoma cell lines, whereas ErbB3 (mean±sd: 4.0% ± 3.6%) and ErbB4 (mean±sd: 1.5% ± 2.1%) are barely expressed at all." (PMID 26496080, 2015).
myopia (3 papers, 2018 to 2025). "It was found that high myopic associated proteins (ASXL1 FGFR3 ERBB3 SOX4) can affect ARID1B protein by affecting ARIDIA protein, and COL2A1 protein can also affect ARIDIA protein by affecting FGFR3 protein, resulting in the clinical phenotype of patients with high myopia." (PMID 38790056, 2024). "Analysis of protein interactions in the STRING online database revealed that the ARID1A protein interacts with the high myopia gene-related proteins FGFR3, ASXL1, ERBB3, and SOX4, whereas the ARID1A protein antagonizes the ARID1B protein." (PMID 38790056, 2024).
neurofibroma (3 papers, 2019 to 2023). An intraneural or extraneural neoplasm arising from nerve tissues and neural sheaths. "Neurofibroma tumor nuclei remain most similar to Schwann cells, with expression of markers such as S100B, PMP2, MPZ and ERBB3." (PMID 37164978, 2023).
renal carcinoma (3 papers, 2014 to 2021). A carcinoma arising from the epithelium of the renal parenchyma or the renal pelvis. "COMMD5/HCaRG overexpression inhibited tumor growth and angiogenesis in a homograft renal carcinoma mouse model by promoting de-phosphorylation of ErbB2/HER2, ErbB3/HER3, and EGFR, leading to inhibition of ErbB signaling pathways." (PMID 33768002, 2021). "Treatment of ACHN renal carcinoma cells led to rapid drop in pERBB3 levels without an effect on total ERBB3 levels." (PMID 25386657, 2014).
sarcoma (3 papers, 2012 to 2023). A usually aggressive malignant neoplasm of the soft tissue or bone. "Currently, no data are available about the activity of ErbB2- or directly ErbB3-targeted therapy in pediatric sarcoma." (PMID 23227212, 2012). "DSRCT tumors did not have a significantly higher level of expression of ERBB3 or ERBB4 mRNA compared to the other sarcomas." (PMID 34841430, 2022). "While tyrosine kinase inhibitors blocking EphA2 or VEGF-C signaling are already being tested as potential targets for sarcomas, no information about the biological role of ErbB3 in pediatric rhabdomyosarcoma is currently available." (PMID 23227212, 2012).
teratoma (3 papers, 2022 to 2025). A non-seminomatous germ cell tumor characterized by the presence of various tissues which correspond to the different germinal layers (endoderm, mesoderm, and ectoderm). "In the current study, we have demonstrated that an expandable and engraftable CD82+ERBB3+NGFR+ skeletal myogenic progenitor population can be produced from human PSCs via teratoma formation." (PMID 36766703, 2023). "Nevertheless, when combined with CD82 and ERBB3, the use of NGFR further purified the skeletal myogenic population in human teratomas." (PMID 36766703, 2023). "Taken together, these results suggested that ERBB3 and CD82 were effective surface markers for identifying and isolating human PSC-derived skeletal myogenic progenitors produced via teratoma formation." (PMID 35563894, 2022). "We further revealed ERBB3 and CD82 as effective surface markers for prospective isolation of teratoma-derived skeletal myogenic progenitors." (PMID 35563894, 2022). "Teratomas were enzymatically digested and mechanically dissociated to produce a single-cell suspension, stained for CD82, ERBB3, and NGFR, and the triple-positive population, representing approximately 2% of total teratoma-derived cells, isolated by fluorescence-activated cell sorting (FACS)." (PMID 40801582, 2025).
thyroid (3 papers, 2015 to 2023). "It is noteworthy that patients of older age or with a medical history of thyroid gland disorder exhibited a significant upregulation of ERBB3 mRNA levels." (PMID 38144565, 2023). "On the protein level, a tissue microarray study in proliferative thyroid lesions found a correlation of ERBB3 expression with LN metastasis whereas ERBB4 expression correlated with lower tumor stage." (PMID 25922907, 2015). "Furthermore, a tumor that develops in the isthmus or a patient with a history of thyroid gland disorder results in lower levels of ERBB3 methylation." (PMID 38144565, 2023).
uterine sarcomas (3 papers, 2024 to 2025). "S100/SOX10-positive uterine sarcoma with ERBB2/ERBB3 mutation is a newly recognized and highly aggressive subtype of uterine sarcoma characterized by aberrant HER2 pathway activation and neural crest-like immunophenotype." (PMID 41463261, 2025). "In summary, we herein describe the first detailed study of a novel ERBB2/ ERBB3-mutated S100/SOX10-positive unclassified highly aggressive uterine sarcoma type." (PMID 39196362, 2024). "Lastly, a recent study introduced a novel group of uterine sarcomas with ERBB2/ERBB3 alterations which also show diffuse S100 positivity and may present as a cervical polyp." (PMID 39387892, 2024). "Our Case 1 falls into this pathogenetic category and represents a novel observation in this type of uterine sarcomas, indicating that mutant ERBB3 concurrent with ERBB2 amplification represents a novel mechanism driving oncogenesis in tumors lacking the V777L ERBB2 mutation." (PMID 39196362, 2024).
virus infection (3 papers, 2016 to 2017). "The mRNA level of ErbB3 is higher in HBV-associated HCC group in comparison to that in non-virus infection HCC (NBNC) group." (PMID 26595522, 2016). "The timing of PKM expression time after virus infection was similar to that of Ebp1, ErbB3 (an epidermal receptor tyrosine kinase)-binding protein and also interacted with PB1 subunit of RdRp, and the elevated levels of PKM lasted until 8 hpi." (PMID 28232820, 2017).
acute myocardial infarction (2 papers, 2018 to 2023). Necrosis of the myocardium, as a result of interruption of the blood supply to the area. "Analysis of RTK expression in the acute myocardial infarction samples revealed 4 RTKs with significantly reduced expression (EGFR, ERBB2, ERBB3 and EPHA2) when compared to healthy heart." (PMID 30342492, 2018). "When comparing healthy hearts with hearts representing acute myocardial infarction, significant downregulation of EGFR, ERBB2, ERBB3, as well as EPHA2, was discovered in the infarcted heart, ERBB2 demonstrating the greatest difference in expression." (PMID 30342492, 2018).
adenoma (2 papers, 2015 to 2019). A neoplasm arising from the epithelium. "Increased expression of ERBB3 in adenomas and adenocarcinomas compared to normal tissues was confirmed by immunohistochemistry." (PMID 26367378, 2015). "EGFR, a subtype of the ErbB receptors, which include EGFR (ErbB1, HER1), p185her2/neu (ErbB2, HER2), ErbB3 (HER3), and ErbB4 (HER4), can regulate cell motility and adhesion, adenoma invasion, angiogenesis, and adenoma cell proliferation." (PMID 31798535, 2019).
allergic disease (2 papers, 2024). An immune response that occurs following re-exposure to an innocuous antigen, and that requires the presence of existing antibodies against that antigen. "Among these, the increased levels of TNFAIP3, ERBB3, TLR1, and IL1RL2 proteins were associated with a reduced risk of allergic diseases, with corresponding odds ratios of 0.82 (0.76–0.88), 0.74 (0.66–0.82), 0.49 (0.45–0.55), and 0.81 (0.75–0.87), respectively." (PMID 38573314, 2024). "Specifically, elevated levels of TNFAIP3, ERBB3, TLR1, and IL1RL2 proteins were associated with a reduced risk of allergic diseases, yielding corresponding odds ratios of 0.82 (0.76–0.88), 0.74 (0.66–0.82), 0.49 (0.45–0.55), and 0.81 (0.75–0.87), respectively." (PMID 38573314, 2024).
bipolar disorder (2 papers, 2009 to 2012). A disorder of the brain that causes unusual shifts in mood, energy, activity levels and the ability to carry out day-to-day tasks. "Two recent candidate genes, ErbB3 and Fgfr1, are growth factors whose mRNA levels have been found to be altered in the leukocytes of patients that are affected by bipolar disorder in a depressive state." (PMID 22989054, 2012).
carcinoid (2 papers, 2021 to 2025). "This included HRAS (11p15) amplification on chromothriptic chromosome 11, KRAS (12q12) and ERBB3 (12q13) amplification on chromosome 12, as well as deletions of key carcinoid-associated tumor suppressor genes MEN1 (11q13) and ARID1A (1p36) on chromosomes 11 and 1, respectively." (PMID 39185963, 2025).
chronic hepatitis (2 papers, 2021 to 2024). An active inflammatory process affecting the liver for more than six months. "These molecular alterations may result in an increased ERBB3 expression in cirrhotic patients compared to those with chronic hepatitis." (PMID 33799723, 2021).
clear cell renal cell carcinoma (2 papers, 2019 to 2024). "This study investigated the expression of ERBB3 isoforms in renal clear cell carcinoma (RCC), utilizing data from 538 patients from The Cancer Genome Atlas (TCGA) Firehose Legacy dataset." (PMID 38276060, 2024).
colitis (2 papers, 2021). Inflammation of the colon. "Surprisingly, in two mouse models of human CRC, the ApcMin model of spontaneous intestinal tumorigenesis and a model of colitis-associated colorectal (CAC) tumorigenesis induced by the colon-selective carcinogen azoxymethane (AOM), ERBB3 deficiency dramatically increased tumor multiplicity." (PMID 34843459, 2021).
depression (2 papers, 2012 to 2022). "Our findings were in agreement with Aston’s microarray data, which found an ErbB3 deficit in the temporal cortex of depressed patients, supporting a role for ErbB3 in the pathogenesis of depression." (PMID 22989054, 2012). "Our results on leukocytes in humans and in animal models support the role of ErbB3 in depression and confirm the usefulness of leukocytes as a peripheral model for studying the biochemistry and molecular biology of the central nervous system." (PMID 22989054, 2012). "Although we did not identify any significant changes in Fgfr1 mRNA levels in leukocytes, an important reduction of ErbB3 mRNA levels emerged in depressed patients, suggesting that ErbB3 could be considered as a biomarker of depression." (PMID 22989054, 2012). "Regarding the role of these two growth factors in antidepressant treatment, studies on animal models of depression indicate that the FGF system may be involved in the response to antidepressants, and there are no studies about ErbB3 in rats." (PMID 22989054, 2012).
dilated cardiomyopathy (2 papers, 2021). Cardiomyopathy which is characterized by dilation and contractile dysfunction of the left and right ventricles. "Although methylation of ErbB3 gene has been reported in human dilated cardiomyopathy; the function of ErbB3 in the adult heart is only now being understood." (PMID 34408653, 2021). "For instance, methylation of the ErbB3 gene has been observed in human dilated cardiomyopathy." (PMID 33988127, 2021).
endometriosis (2 papers, 2017 to 2019). The growth of functional endometrial tissue in anatomic sites outside the uterine body. "Lastly, growth and angiogenic factors like Angiopoietin 1 (ANG-1), Angiostatin, Lipocalin-2, and ErbB3 were decreased in endometriosis patients, while IGF-1 was significantly elevated in diseased patients." (PMID 31333337, 2019).
Esophageal Neoplasms (2 papers, 2017 to 2021). "Previous research showed that hsa-miR-125b (2nd in the prediction list) can promote cell proliferation in Esophageal Neoplasms by influencing the target transcripts: CYP24, ERBB2 and ERBB3." (PMID 28339468, 2017).
ganglioneuroblastoma (2 papers, 2013 to 2023). A neuroblastic tumor characterized by the presence of neuroblastic cells, ganglion cells, and a stroma with Schwannian differentiation constituting more than fifty-percent of the tumor volume. "Additionally, a study referred to the role of ERBB3 as a marker of a ganglioneuroblastoma/ganglioneuroma-like expression in neuroblastic tumors." (PMID 37218882, 2023).
Hepatitis B (2 papers, 2016 to 2022). "Similarly, ERBB3 is overexpressed in hepatitis B-associated HCC, which are sensitive to ERBB3 inhibition." (PMID 35433463, 2022).
Insulin resistance (2 papers, 2020 to 2022). Increased resistance towards insulin, that is, diminished effectiveness of insulin in reducing blood glucose levels. "Stress-induced p38MAPK activation leading to the activation of ERBB3 was shown to be related to insulin resistance in a mouse model." (PMID 36551281, 2022). "Overexpression of ERBB3 may enhance PI3K activity and implicating ERBB proteins in stress-induced insulin resistance." (PMID 32831068, 2020).
kidney cancer (2 papers, 2021 to 2022). Primary or metastatic malignant neoplasm involving the kidney. "Here, our results indicate that NEDD4L can also degrade ERBB3 in kidney cancer cells." (PMID 34539897, 2021).
lethal congenital contracture syndrome 2 (2 papers, 2020 to 2024). "Lethal Congenital Contracture Syndrome 2 (LCCS2) is caused by mutations in the ERBB3 gene on chromosome 12q13.2." (PMID 39457470, 2024).